IL15 (interleukin 15)
Diseases named in the same sentence as IL15 in open-access papers (continued):
Sharing a sentence is not in itself a finding about the gene and the disease.
tumor (continued). "Within the NKim subcluster, gene expression of key receptors and cytokines (Il15, CXCR3, KLRG1) correlated significantly with tumor grade." (PMID 40821787, 2025). "To further link tonic signaling score with antitumor activity, we analyzed the single cell RNA-seq dataset from CAR-T clinical trials in liver tumors 64, in which IL-15–engineered CAR-T cells displayed enhanced expansion, persistence, and tumor control." (PMID 41256549, 2025). "Lentiviral overexpression of murine IL-15 and CCL17 delays CCA tumor progression in a syngeneic transplant model." (PMID 41332325, 2025). "IL-15 plays a critical role in the survival and homeostasis of CD8+ T cells and NK cells, while IL-12 shifts the tumor microenvironment toward an immunostimulatory state through IFN-γ induction." (PMID 41302038, 2025). "Several preclinical and early-phase clinical studies have demonstrated that IL-15 promotes homeostatic proliferation and supports long-term survival of CAR T and CAR NK cells, translating into improved tumor control in solid and hematologic malignancies." (PMID 40564987, 2025). "To address challenges inherent in co-administering IL-15 with CAR-T cells targeting the tumor microenvironment, we developed a novel CAR construct that incorporates intrinsic IL-15 secretion capacity directly into FAP-targeted CAR-T cells." (PMID 41455698, 2025). "Fourth-generation PD-L1 CAR-NK cells co-expressing IL-15 further enhanced the persistence and functionality of CAR-NK cells against various tumor cell lines." (PMID 41511303, 2025). "The therapeutic efficacy of the combination therapy of IL-15 and NIR-PIT was first evaluated using the highly-immunogenic MC38-Luc tumor model." (PMID 41410776, 2025). "NK cells also express receptors for activating cytokines, such as IL-15, IL-12, IL-18, and IL-21, as well as receptors for suppressive factors such as TGF-β and prostaglandin E2 present in the tumor microenvironment." (PMID 39835538, 2025). "GPC3-targeting CAR-T cells with dual cytokine expression of IL-15 and IL-21 exhibited enhanced antitumour activity against HCC, demonstrating superior proliferation, persistence, and tumour regression in GPC3-positive xenograft models." (PMID 40624498, 2025). "Despite having higher death rates than the IL-15 NK cells, the higher proliferation pc, cytotoxicity pkill, and SKC S0 of the IL-21 NK cells contributed to more rapid tumor control." (PMID 40027823, 2025). "In the TME, IL-15 complexes and anti-PD-1 mAb localization differ from those in the TDLN, where IL-15 complexes appear to be maintained proximal to the injected area (tumor interior)." (PMID 41373645, 2025). "ACTM-838 utilizes the STACT platform to deliver IL-15/IL15Rα and a constitutively active STING to tumor-resident phagocytic antigen-presenting cells." (PMID 41048107, 2025). "In this study, we demonstrate that arming CAR-NK cells with IL-21 enhances their effector function and provides long-lasting anti-tumor activity through metabolic reprogramming, compared to CAR-NK cells modified to express with IL-15." (PMID 40176196, 2025). "In murine models of metastatic colon adenocarcinoma, localized IL-15 expression from VSV significantly improved survival and promoted tumor clearance." (PMID 40507337, 2025). "For instance, the JAK-STAT pathway is related to the inflammatory response mediated by cytokines like IL-2, IL-15, and IFN, and its excessive activation can promote tumor development." (PMID 41471272, 2025). "Fourth-generation CARs that incorporate cytokines (IL-7, IL-15, or IL-21) increase CAR-T-cell persistence, tumor targeting, and antitumor activity." (PMID 41019073, 2025). "It has been observed that cytokines such as IL-2, IL-12, IL-15, IL-18, and TGF-β can modulate the anti-tumor immune response mediated by NK cells, offering new strategies and choices for immunotherapy by regulating the function and activity of NK cells." (PMID 39221244, 2024).
tumor (continued). "ELISA reveals that XLLXF combined with trastuzumab increases the levels of IL-15, IL-2, TNF-α, and IFN-γ in tumor-bearing mice." (PMID 38379418, 2024). "Various genes with tumor suppressor functions, such as chemokine ligand-11, IL-21, IL-27, CD40L, chemokine ligand-9, IL-9, and IL-15, were upregulated in DBMSCs after treatment with MDA231 cells in an IC setting." (PMID 39768220, 2024). "The results showed that XLLXF combined with trastuzumab significantly increased the levels of IL-15, IL-2, TNF-α, and IFN-γ in the sera of tumor-bearing nude mice." (PMID 38379418, 2024). "For instance, in a preclinical glioma model, IL-15 expression led to increased persistence and proliferative capacity of IL-13Rα2-CAR-T cells, resulting in enhanced anti-tumor activity." (PMID 38932383, 2024). "A variety of cell types, such as macrophages and dendritic cells, can release IL-15, which can drive CD8+ T cells and NK cells to proliferate faster and be more effective against tumours." (PMID 39596267, 2024). "In a mouse model of luminal B mammary adenocarcinoma, fluorescently labeled IL-15 localized with CD8+ T-lymphocytes and natural killer cells found in the tumor and in the lymph nodes in the local lymphatic drainage." (PMID 38928185, 2024). "The combination of the tumor-priming oxygen release, CAR T cells, and IL-15 promoted the efficacy of the platform to kill cancerous cells." (PMID 37587290, 2024). "Treatment with IL‐15 or anti‐TIGIT resulted in significant suppression of tumour progression; notably, treatment with IL‐15 exhibited the most significant inhibition of tumour growth in Tigit−/− mice." (PMID 38279870, 2024). "IL-15 induces NKp30 expression on human circulating CD8+ T cells, which exert an NK-like anti-tumor effect." (PMID 38698855, 2024). "Based on this mechanism, IL-15 superagonist has been developed and shown to significantly enhance NK cells and CD8+ T cells’ anti-tumor efficacy in cancer models." (PMID 38368374, 2024). "Research conducted by our group has already demonstrated that peripheral blood-derived NK cells exhibit increased potency to kill PDAC tumor and CAF cell lines when prior stimulated with IL-15." (PMID 38331849, 2024). "IL-33 exerts pro-tumor activity, including PPAR-gamma-mediated delivery of IL-4, IL-13, and IL-15 from ILC2s." (PMID 39119332, 2024). "IL-15 stimulates CD8+ T cells and NK cells, enhancing the anti-tumor activity of adoptively transferred T cells." (PMID 38904025, 2024). "In mouse models, compared to mice that received conventional CAR-NK cells, mice treated with IL-15-secreting CAR-NK cells exhibit high plasma concentration of IL-15, high proliferation and persistence of CAR-NK cells, and more tumor shrinkage." (PMID 40007761, 2024). "Utilizing proliferative cytokines such as IL-2 and IL-15 has demonstrated the ability to enhance the effectiveness of CAR-T cells, resulting in robust anti-tumor activity." (PMID 38402232, 2024). "IL-12, IL-18, and IL-15 are the most widely used cytokines that enhance the cytotoxic efficacy of TRUCK CAR-T cells and reduce tumor mass." (PMID 39312080, 2024). "The administration of IL‐15 and anti‐TIGIT was tested using a transplanted tumour murine model and PDO model, which provided strong support for this conclusion." (PMID 38279870, 2024). "When comparing the tumour tissues to the healthy lung tissues, there was a notable increase in TGF‐β and IL‐10 concentrations as well as a decrease in IL‐15 levels, implicating an immunosuppressive microenvironment favouring tumourigenesis of LUAD." (PMID 38279870, 2024). "The secreted cytokines IL-7, IL-12, IL-15, or IL-18 not only enhance the survival capacity of CAR–T cells and augment their cytotoxic activity but also attenuate the immunosuppressive tumor microenvironment." (PMID 39220130, 2024).
tumor (continued). "The results of the study showed that combined treatment with IL-7 and IL-15 induced the recruitment and activation of TIL-Ts, which disrupted tumour cell growth and ultimately led to the regression of the primary osteosarcoma." (PMID 38675377, 2024). "Specifically, alterations in cytokines such as IL32, IL22, IL17F, IL17A, IL16, IL15, and HMGB1 can create an immunosuppressive tumor microenvironment in CTCLs to facilitate immune evasion and tumor progression." (PMID 39409988, 2024). "Common cytokines used in TRUCKs include interleukin (IL)-2, IL-15, and IL-18, which enhance the immune response against solid tumours and extend the persistence of CAR-T cells within the tumour microenvironment." (PMID 39596267, 2024). "Then, freezing solution or 5 × 106 cells of either Mock-NK, IL-15△ CAR-NK, or 12 C CAR-NK cells were infused intravenously on day 11 after tumor engraftment and Jurkat-Luc cell growth was monitored by in vivo imaging as planned." (PMID 39462383, 2024). "When delivered intra- tumorally, both MS~IL-15 and MS~RLI had modest anti-tumor efficacy, but high anti- metastatic activity." (PMID 39559362, 2024). "The variables included were ECOG, tumor stage, the indication for treatment, the type of ICI, the best response, LDH, IL-2 and IL-15." (PMID 39199571, 2024). "Thus, we first examined whether the overexpression of IL-15 alters Cdc42 activity in tumor cells." (PMID 38637902, 2024). "Recombinant Newcastle disease virus strains expressing cytokines such as IL-2, IL-15, or TRAIL stimulate tumor-specific CTL responses, inducing CD4+ and CD8+ T cell proliferation, leading to tumor regression." (PMID 38731910, 2024). "Administration of IL-15:IL-15Ra complexes combined with isotype control Abs mediated the greatest control of tumor growth, while CD8 T cell depletion resulted in faster tumor growth than in PBS control mice given isotype Abs." (PMID 38267402, 2024). "Among the test groups, the hydrogel with IL-15 and CDDP suppressed the tumor growth more efficiently." (PMID 37587290, 2024). "Miller team incorporated a modified IL-15 cross-linker to construct a TriKE bearing scFv against CD16 on NK cells and CD33 on tumor cells (named GTB-3550), which can potently restore defective NK function and induce specific NK cell proliferation." (PMID 39664443, 2024). "Using PDOs co-cultured with CAFs they showed that CD70-CAR-NK cells in combination with IL-15 is needed for an effective eradication of low- and high-expressing CD70 + tumor cells and CAFs." (PMID 39261955, 2024). "This led to priming the tumor for CAR T cells and IL-15, which were able to migrate from the carrier to the tumor following gel degradation." (PMID 37587290, 2024). "Immunofluorescence staining in tumour-bearing liver from KPC mice and littermate controls confirmed that the CCR5 ligands CCL3, CCL4 and CCL5, and the cytokines IL-12, IL-15 and IL-18 were produced by KCs in peritumoural liver." (PMID 38326607, 2024). "Co-expression of transgenic IL15 significantly increased GD2.CAR-T engraftment and also promoted additional sustained tumor control." (PMID 38558810, 2024). "Consistently, quantification of activated natural killer (NK) cells and CD8+ T cells in the metastatic liver showed that they were also preferentially enriched at the tumour margin, next to KCs expressing CCL3, CCL4, CCL5, IL-12, IL-15 and IL-18." (PMID 38326607, 2024). "This process is facilitated by the production of various cytokines and chemokines, including TNF-α, IFN-γ, IL-2, IL-12, IL-21, IL-15, IL-18, CXCR3, and granulocyte-macrophage colony-stimulating factor (GM-CSF), which actively promote anti-tumor immunity." (PMID 38533507, 2024). "For example, in pancreatic cancer, following aerobic exercise an anti-tumor immune cells redistribution occurs characterized by an accumulation of interleukin (IL)-15 and CD8+ T cells in the tumor microenvironment, which are hurdle against tumor growth." (PMID 39555455, 2024).
tumor (continued). "Combination therapy with recombinant IL-15 and blocking antibodies against CTLA-4 has been shown to increase survival and reduce tumor growth in murine tumor models, as compared to one of the treatments alone." (PMID 39204319, 2024). "IL-15 can also induce the expression of NKG2D, a natural cytotoxicity receptor that can recognize stress-induced ligands on tumor cells." (PMID 39199421, 2024). "IL-15 is known to stimulate CD8 T cell proliferation and regulate tumor reactive lymphocyte numbers in the tumor microenvironment." (PMID 38690288, 2024). "When IL-15 anti–programmed cell death ligand 1 (PD-L1) and anti–cytotoxic T-lymphocyte antigen 4 (CTLA-4) antibodies were used together in mouse tumor models, the latter were able to survive for a longer time." (PMID 39507777, 2024). "We posit that there are multiple circumstances where IT administration of MS~IL-15 agonists in combination with systemic or local administration of other agents could provide dual benefits of anti-tumor and anti-metastatic effects, without the toxicities associated with systemic IL-15." (PMID 39559362, 2024). "IL‐15 has been used clinically in tumor therapy, where it recruits CD8+ T cells and NK cells to the tumor site, leading to the secretion of XCL1 and the subsequent attraction of dendritic cells expressing XCR1 receptors." (PMID 38887195, 2024). "Combining IL-15 with PD-L1 and CTLA-4 blockade has been shown to improve antitumor immunity, slow tumor growth, and prolong animal survival in several preclinical studies." (PMID 39507777, 2024). "The anti-PD-1/IL-15 immunocytokine, as reported by Fu team, induced the complete demise of MC38 tumor-bearing mice when administered intraperitoneally twice at a dosage of 30 μg." (PMID 39664443, 2024). "Gene-based delivery of IL-15/IL-15Rα to tumor cells, shows expansion of NK cells, activation of NK cells, CD4+ and CD8+ T cells, and killing of tumor spheroids." (PMID 37923822, 2023). "This approach can revolutionize traditional cytokine therapy by inducing safer and more efficient CTL immune responses against tumors by spatiotemporal integration of multivalent IL-15 self-transpresentation (MIST) and tumor antigen presentation." (PMID 37875481, 2023). "IL-15 can up-regulate TIGIT and CD226 via tumor-infiltrating NK cells, increasing NK cell-mediated cytotoxicity and reducing tumor metastases." (PMID 37494663, 2023). "High IL-15 expression can support ALL development and proliferation and can influence the tumor microenvironment interactions, leading to differences in minimal residual disease and treatment response." (PMID 37153603, 2023). "IL-15 depletion resulted in impaired ILTCK expansion and differentiation, as well as accelerated tumor growth in vivo, which was consistent with our findings." (PMID 37348499, 2023). "Several pro-inflammatory cytokines released by M1-activated macrophages, including IL-12, IL-15, IL-18, and TNF-α, are critically involved in the improvement of NK cell anti-tumor function." (PMID 37298470, 2023). "It has been suggested that the IL-15-conjugated CD28-CAR structure reduces exhaustion markers, upgrades persistence, and enhances the anti-tumor function of CAR-NKT cells." (PMID 37158883, 2023). "We studied the γc cytokines IL-2, IL-7, IL-15 and IL-21 or IFN-γ, as these cytokines have been shown to stimulate anti-tumor immunity." (PMID 37923822, 2023). "The effects of cyto-IL-15 and ADU-S100 on immune activation were investigated by measuring the release of cytokines in blood plasma and tumor lysates after 6 days of treatment using a cytokine bead array." (PMID 37465665, 2023). "Upon tumor challenge, CAR-T cells exposed to IL-15 exhibited fewer apoptotic features, higher proliferative capacity, and a superior antitumor response than those exposed to IL-2 in vivo." (PMID 38049832, 2023).
tumor (continued). "Moreover, CAR-T cells secreting IL-7, IL-12, IL-15, IL-18, IL-33, and IL-36γ have also exhibited improved persistence or anti-tumor ability in preclinical or clinical trials; however, the continuous expression of pro-inflammatory cytokines such as IL-12 may lead to systemic toxicity." (PMID 37596653, 2023). "Recent studies have found that tumor-infiltrating NK cells and CD8+ T cells activated by IL-15 upregulate the secretion of a chemokine named XCL1." (PMID 37251333, 2023). "These discoveries emphasize the complex spectrum of IL-15 modulation by various molecular agents, illuminating promising pathways for the therapeutic manipulation of ILT cells to enhance their robust anti-tumor response." (PMID 37892995, 2023). "IL-15 is critical for proliferation and activation of NK cells and CD8+ T cells, leading to stronger tumor-clearance efficacy." (PMID 37144558, 2023). "Enhanced anti-tumor efficacy of CAR T cells with constitutive IL-7 and IL-15 signaling has also been reported, as well as with the inducible release of an IL-15 super-agonist complex by T cells upon interaction with the cognate antigen." (PMID 36721153, 2023). "IL-15 is a highly effective activator of effector CD8+ T cells, the primary anti-tumor population of T cells, making it a valuable target to enhance anti-tumor immunity." (PMID 37296860, 2023). "It's a heterodimeric fusion protein containing soluble TGF-βRII and IL-15/IL15RαSu, which can neutralize TGF-β (inhibiting tumor progression and relieving immunosuppression) and directly activate immune cells." (PMID 37251333, 2023). "As stated, CCL2, CXCL12, IL-15, CD20, and CD70 are immune-related genes that have a certain significance for tumor development and immunotherapy." (PMID 37494663, 2023). "MSCs are able to deliver a variety of cytokines and growth factors to the tumor site that were identified as anti-tumor agents, comprising IFN-α, IFN-β, IFN-γ, IL-2, IL-7, IL-12, IL-15, IL-18, IL-25, and NK4, an antagonist of HGF." (PMID 37686315, 2023). "We propose that the divergent anti-tumor activities of KD033 in PD-L1- and PD-L1+ tumors provide evidence for PD-L1 targeting of IL-15 in vivo." (PMID 36454338, 2023). "This keeps Pro-IL-15 inactive until it accumulates in the tumor and is cleaved by the high MMP environment of the tumor microenvironment." (PMID 36936961, 2023). "In recent years, some cytokines, including IL2, IL12, IL15, IL21, GM-CSF, and interferon-α, have been found to regulate the composition of tumor microenvironment and modulate the efficacy of immune therapy in murine cancer models." (PMID 36959575, 2023). "After a literature review, we collect factors that directly regulate the function of NK cells, and the gene list is IL2, IL15, IL18, IL21, all of which promote NK cell-mediated tumor death, while IL6, TGFβ and TNFα promote NK cell exhaustion." (PMID 38159250, 2023). "We observed significant increases in the expression of proinflammatory cytokines and chemokines such as Ifng, Tnf, Il15, Il18, Cxcl9, Cxcl10, Cxcl12 and Ccl5 in AC484-treated tumours." (PMID 37794185, 2023). "He, Chen and co-workers developed an mPEG-b-PELG hydrogel co-loaded with interleukin-15 (IL-15) and CDDP for tumor immuno-chemotherapy." (PMID 37265604, 2023). "Mice with TRAMP-C2 tumors treated with combination of cyto-IL-15 and ADU-S100 on the right flank and eventually cured of their tumor, were rechallenged in the distal (left flank) with TRAMP-C2 cells." (PMID 37465665, 2023). "While NK cell expansion using K562-mb-IL-21 feeder cells and IL-15 stimulation can enhance NK cell metabolic fitness allowing them to thrive in the TME, efficient homing of adoptively transferred NK cells to the tumor remains to be addressed." (PMID 38022679, 2023). "Similar to their results for IL-15, anti-EGFRvIII CAR T-cells co-expressing IL-18 had reduced expression of exhaustion markers and superior anti-tumor activity." (PMID 38201551, 2023).